MGST3 (microsomal glutathione S-transferase 3)
Description:
Displays both glutathione S-transferase and glutathione peroxidase activities toward oxyeicosanoids, as part of cellular detoxification as well as synthesis of bioactive metabolites. Catalyzes conjugate addition of reduced glutathione to the alpha, beta-unsaturated C=C carbonyl group of eisosanoids such as leukotriene A4 and 15-deoxy-Delta12,14-prostaglandin J2 to form GSH adducts relevant to the inflammatory response. Catalyzes glutathione-dependent reduction of eicosanoid peroxides to yield the corresponding eicosanoid hydroxides.
Synonyms: GST-3; GST-III
Tractability: Antibody: UniProt predicts a signal peptide or a membrane-spanning region. PROTAC: ubiquitination databases record sites on it; its protein half-life has been measured.
Target class: Enzyme
Gene: Protein-coding gene on chromosome 1 (165,630,874 to 165,661,796, forward strand). Ensembl gene ENSG00000143198.
Subcellular location: Mitochondrion outer membrane
Subcellular location (Human Protein Atlas): Nucleoplasm
Pathways (Reactome):
Metabolism: Aflatoxin activation and detoxification; Glutathione conjugation
Gene Ontology:
Molecular function: glutathione peroxidase activity; glutathione transferase activity; identical protein binding; leukotriene-C4 synthase activity; protein binding; phospholipid-hydroperoxide glutathione peroxidase activity
Biological process: leukotriene biosynthetic process; lipid metabolic process; prostanoid metabolic process; arachidonate metabolic process; cellular oxidant detoxification; leukotriene metabolic process
Cellular component: membrane; mitochondrial outer membrane; mitochondrion; endoplasmic reticulum; endoplasmic reticulum membrane; nuclear envelope
Genetic constraint (gnomAD): Loss-of-function variants: 19 observed, 22.49 expected, observed/expected ratio (o/e) 0.84, 90% interval 0.59 to 1.24. The synonymous counts are far from expectation, so gnomAD's model fits this gene poorly and the ratio says little. Missense variants: 155 observed, 202.85 expected, observed/expected ratio (o/e) 0.76, 90% interval 0.67 to 0.87. Synonymous variants: 49 observed, 72.22 expected, observed/expected ratio (o/e) 0.68, 90% interval 0.54 to 0.86.
Homologues: Orthologues: chimpanzee MGST3 (99% identical), macaque MGST3 (98% identical), dog MGST3 (93% identical), pig MGST3 (89% identical), guinea pig MGST3 (88% identical), mouse Mgst3 (86% identical), rat Mgst3 (86% identical), rat Utp3 (83% identical), tropical clawed frog mgst3 (74% identical), rabbit MGST3 (72% identical), zebrafish mgst3a (59% identical). Paralogues in human: MGST2 (32% identical), LTC4S (25% identical), ALOX5AP (20% identical).
Diseases named in the same sentence as MGST3 in open-access papers:
MGST3 is named in the same sentence as 27 diseases in open-access papers, as found by Europe PMC text mining. Sharing a sentence is not in itself a finding about the gene and the disease. The quoted sentences say what the papers report.
breast carcinoma (6 papers, 2014 to 2024). "Our analysis revealed that mutations in OSRE such as MGST3, GSTP1, NDUFS2, NDUFS8 and PRDX6 were particularly prevalent in breast cancer, and for the five genes the most prevalent genetic alteration was amplification." (PMID 39594421, 2024). "Unique mutations in genes such as NDUFS2, MGST3, PRDX6, NDUFS8, and GSTP1 were found predominantly in breast cancer." (PMID 39594421, 2024). "RT-qPCR experiments confirmed that our breast cancer cell lines express all three MGSTs (MGST1/MGST2/MGST3) at steady states." (PMID 36293074, 2022). "The cis-eQTL associations of 7 genes (TAPBPL, H1F0, SERPINB9, HMBOX1, MGST3, TMBIM4, THNSL2) are shared between GBM and cell lines/normal tissues; the association of 4 genes (TAPBPL, H1F0, HMBOX1, THNSL2) are common between GBM and Breast Cancer." (PMID 25133526, 2014). "High expression of MGST3 and USP53 was also correlated with poor clinical outcome in HER2-positive breast cancer, although the contribution of these two genes to brain metastasis has not been reported." (PMID 32640677, 2020).
Alzheimer disease (2 papers, 2014 to 2016). A progressive, neurodegenerative disease characterized by loss of function and death of nerve cells in several areas of the brain leading to loss of cognitive function such as memory and language. "To support a specific link between genes that are coexpressed with Mgst3 and Alzheimer’s disease we used the exon array data from GeneNetwork, as this is specific to the hippocampus." (PMID 25280473, 2014). "We identify, MGST3 [Entrez: 4259] and use a systems-genetics approach that links this gene to neurodegenerative disorders such as Alzheimer’s disease and Parkinson’s disease." (PMID 25280473, 2014). "Conversely, downregulation of Mgst3 has been observed in Alzheimer’s disease." (PMID 26829228, 2016). "MGST3 has previously been found to be down-regulated in Alzheimer’s disease." (PMID 25280473, 2014).
cervical cancer (1 paper, 2020). A primary or metastatic malignant neoplasm involving the cervix. "Our results also showed that the protein expression of MGST3, AKR1C2, and ERLIN1 decreased in cervical cancer cells in the presence of AS-IV." (PMID 32265995, 2020).
Cirrhosis (1 paper, 2021). A chronic disorder of the liver in which liver tissue becomes scarred and is partially replaced by regenerative nodules and fibrotic tissue resulting in loss of liver function. "Targets affected only by NAFLD-associated cirrhosis were CYP2C8,MGST1, MGST3, UGT2B4, FMO5, and BSEP, while targets that showed asignificant reduction only with cancer-associated cirrhosis were CYP2E1and UGT1A6." (PMID 34428046, 2021). "Wealso quantified nine non-CYP and non-UGT metabolizing enzymes, residentin the endoplasmic reticulum, in all stages of cirrhosis severity,of which, MGST1, MGST3, and FMO5 are reported for the first time incirrhosis." (PMID 34428046, 2021). "For mild cirrhosis,median abundance was significantly lower than the control for onlyfour proteins: CES1 (by 47%, p = 0.003*), FMO3 (by37%, p < 0.001**), EPHX1 (by 41%, p = 0.005*), MGST3 (by 51%, p = 0.003*), MRP2 (54%, p < 0.001**), and OATP1B1 (by 54%, p < 0.001**)." (PMID 34428046, 2021).
colon adenoma (1 paper, 2016). An adenoma that arises from the colon. "Besides, GSTM3 and also MGST3 (Microsomal Glutathione S-Transferase 3) were induced in human colon adenoma cells by the chemoprotector butyrate, while not in highly transformed neoplastic colorectal cells." (PMID 27206673, 2016).
esophageal squamous cell carcinoma (1 paper, 2023). Esophageal squamous cell carcinoma (ESCC) is a type of esophageal carcinoma (EC) that can affect any part of the esophagus, but is usually located in the upper or middle third. "A previous study showed that overexpression of MGST3 significantly promotes the progression of esophageal squamous cell carcinoma." (PMID 37280525, 2023).
hearing loss (1 paper, 2023). "Genetic variants in SOD2 and MGST3 are proposed as mechanistically associated with cisplatin-induced hearing loss." (PMID 37568739, 2023).
lung adenocarcinoma (1 paper, 2023). A carcinoma that arises from the lung and is characterized by the presence of malignant glandular epithelial cells. "Overexpression of MGST3 was found in cisplatin resistant lung adenocarcinoma cells compared to non‐resistant progenitor cells, and when MGST3 expression was increased (via antagonism with its microRNA regulator, mir‐432‐5p) the progenitor cells demonstrated increased survival to cisplatin treatment." (PMID 35906899, 2023).
Obesity (1 paper, 2018). Accumulation of substantial excess body fat. "This study is a first step towards the identification of biomarkers for early-stage obesity (GSTT1, GSTT3, GSTM1, MGST1, MGST3, SOD2, CAT) and glucose load (CRYM) in cattle." (PMID 30235219, 2018).
osteoporosis (1 paper, 2020). A condition of reduced bone mass, with decreased cortical thickness and a decrease in the number and size of the trabeculae of cancellous bone (but normal chemical composition), resulting in increased fracture incidence. "Herein, we first found the significant expression of PLEKHA2, PLEKHB1, PNPLA7, SCD, MGST3 and TSNAX in osteoporosis of postmenopausal women, which may be valuable in understanding the pathology mechanism of the disease." (PMID 32496000, 2020).
renal carcinoma (1 paper, 2015). A carcinoma arising from the epithelium of the renal parenchyma or the renal pelvis. "We also made use of TCGA clear cell data to examine the frequency of mutation of ALDH9A1, MGST3, LOC440700 and TMCO1 in renal cancer." (PMID 25826619, 2015).
rheumatoid arthritis (1 paper, 2020). A chronic, systemic autoimmune disorder characterized by inflammation in the synovial membranes and articular surfaces. "Microsomal glutathione S‐transferase 3 (MGST3), an oxidative stress protein, is associated with rheumatoid arthritis." (PMID 32496000, 2020).
schizophrenia (1 paper, 2021). A major psychotic disorder characterized by abnormalities in the perception or expression of reality. "We also report the following modules of unknown relevance to schizophrenia: Glucuronidation with FDR= 8.81E−04 (genes UGT1A3 to UGT1A10) and Phase II - Conjugation of compounds with FDR= 5E−03 (SLC35B3, GGT7, MGST3, and UGT1A3 to UGT1A10)." (PMID 33892787, 2021).
cancer (7 papers, 2016 to 2024). A tumor composed of atypical neoplastic, often pleomorphic cells that invade other tissues. "Downstream trait analysis in the BXD family supports involvement of Mgst3 in detoxification and oxidative stress pathways and hints at novel roles in pathways involved in cancer, cell growth, and behavior." (PMID 26829228, 2016). "In liver, the expression of syndecan binding protein (Sdcbp, r = 0.48), an adaptor protein thought to modulate multiple signaling pathways whose expression is altered in a number of different cancers, is regulated from the Mgst3 locus." (PMID 26829228, 2016). "Taken together, systems genetics analysis across the BXD family supports a role for Mgst3 in oxidative stress and metabolic pathways and suggests a possible novel role in cell growth signaling pathways often disrupted in many cancers." (PMID 26829228, 2016). "In addition, down-regulation of ALOX5, MGST2, and MGST3 genes using specific siRNAs also decreased platelet-induced cancer cell wound closure and cell migration rate." (PMID 36293074, 2022).
tumor (7 papers, 2014 to 2024). "The deletion of CYP8B1 and amplification of MGST3 were simultaneously associated with tumor grade, stage, and LNM in ESCC." (PMID 36168622, 2022). "The expression of TAPBPL, SERPINB9, RCAN1, TMBIM4, JUNB, IL4R, and LY75 is significantly up-regulated in tumor samples with their high expression associated with a poor outcome; the expression of MGST3 is down-regulated in tumor samples with its low expression associated with poor prognosis." (PMID 25133526, 2014). "PTGDS (Prostaglandin D2 Synthase) and HPGD (15-Hydroxyprostaglandin Dehydrogenase) are enriched in the tumor region, while MGST3 (Microsomal Glutathione S-Transferase 3) is depleted in the tumor region in tissue section 1.2." (PMID 32103057, 2020). "Notably, BRCA patients showed a higher frequency of simultaneous mutations in MGST3, NDUFS2, and PRDX6, while co-occurring mutations were less frequent in other tumor types." (PMID 39594421, 2024). "Additionally, eight genes (ABCG2, ALDH3A1, FXYD2, GST-π1, GST-ω1, HMGCR, MGST1, and MGST3) were upregulated among the G1-G4 DDP-resistant tumor tissues." (PMID 32158694, 2020). "Western blotting analysis revealed that six proteins (MGST1, MGST3, ABCG2, FXYD2, ALDH3A1, and GST-ω1) were differentially expressed among G1-G4 DDP-resistant tumor tissues." (PMID 32158694, 2020). "The protein expression levels of MGST1, MGST3, ABCG2, and FXYD2 differed among the G1-G4 DDP-resistant tumor tissues." (PMID 32158694, 2020). "Therefore, to further confirm that they indeed change at protein level consistent with the genome level, we performed IHC in tissue arrays to examine the protein levels of MGST3 and CYP8B1 in ESCC tumor tissues and adjacent normal tissues." (PMID 36168622, 2022).
neurodegenerative disease (2 papers, 2023 to 2024). A disorder of the central nervous system characterized by gradual and progressive loss of neural tissue and neurologic function. "Recently, it has been shown that MGST3 is co-expressed with genes associated with hippocampal size reduction in neurodegenerative diseases: Huntington’s disease, Alzheimer’s disease, and Parkinson’s disease." (PMID 39000460, 2024). "Pleiotrophin deletion upregulates caspase 6, which is associated with axonal degeneration and neurodegenerative diseases, and the deleterious effects produced can be partially compensated for by the simultaneous induction of the neuroprotective gene MGST3." (PMID 39000460, 2024). "This evidence provides a new therapeutic target for MGST3 as a molecule that regulates the interaction of α-syn with UBL3 in neurodegenerative diseases." (PMID 39000460, 2024). "In this way, we will be able to fully interpret the effect of MGST3 on the interaction between α-syn and UBL3, providing reliability and therapeutic prospects for the treatment of neurodegenerative diseases." (PMID 39000460, 2024).
MGST3 also shares sentences with these, for which no sentence is quoted: adenoma (1 paper); alcohol (1); glioma (1); gynecological tumor (1); hepatoma (1); infection (1); lung carcinoma (1); melanoma (1); non-small cell lung carcinoma (1); pancreatic cancer (1); urothelial cell carcinoma (1).